VIM (vimentin)
Diseases named in the same sentence as VIM in open-access papers (continued):
Sharing a sentence is not in itself a finding about the gene and the disease.
tumor (continued). "Immunohistochemistry showed LCN2, snail, and vimentin protein expression were increased and E-cadherin protein expression was decreased in tumor tissues derived from RGS10-depleted SKBR3 cells compared to NC." (PMID 39145770, 2024). "Vimentin signals were also observed in cells (putative tumor cells or activated microglia) outside of blood vessels; with similar observations after 4x expansion." (PMID 38295184, 2024). "Then, we examined the expression of some indicators of epithelial–mesenchymal transition (EMT) process (E‐cadherin, N‐cadherin, vimentin), which are so closely related to tumour metastasis." (PMID 39663596, 2024). "Vimentin was identified as an independent predictor of tumor budding (odds ratio of 2.738, 95% CI [1.519–4.934]; p = 0.001)." (PMID 39061649, 2024). "Western blot analysis also showed the increased phosphorylated NF-κB and Vimentin expression and decreased E-cadherin expression in tumor cells co-cultured with CXCR1+ neutrophils, which reversed upon addition of reparixin." (PMID 39638994, 2024). "The extent of the research gap filled is that we have been able to validate the utility of CD44, EGFR, E-Cadherin, and vimentin as indicators of tumor aggressiveness and recurrence." (PMID 39050298, 2024). "In this study, EMT was assessed immunohistochemically through changes in E-cadherin and vimentin expression in invasive tumor regions, and the expression of galectin-3 was investigated in these areas." (PMID 39451592, 2024). "The mesenchymal markers, such as N-cadherin, Vimentin, Fibronectin, Snail, Slug, and Twist, promote tumor cells to become more malignant and increase their invasiveness and metastatic activity." (PMID 38279345, 2024). "Mucin-1 and Vimentin were independent predictors of tumor differentiation (p = 0.006) and budding (p = 0.001), respectively." (PMID 39061649, 2024). "All 4 demonstrated diffuse strong positivity for mammaglobin, GATA3, and S100, as well as expression of vimentin in more than 25% of tumor cells." (PMID 37306115, 2024). "Otherwise, enhanced E-cad’s expression and reduced expression of N-cad and Vimentin were present in tumor tissues of the METTL16 knockdown group." (PMID 39061113, 2024). "It exerts its anti-tumor effects by down-regulating the expression of Vimentin and MMP-9 and up-regulating the expression of E-cadherin." (PMID 39193331, 2024). "The peaks of epithelial cells and tumor cells were notably enriched in the gene sets of ‘VIM, KRT5, KRT17’ and ‘KRT8, KRT18, FOXA1’, respectively." (PMID 38581422, 2024). "Conversely, vimentin, an intermediate filament characteristic of mesenchymal cells, begins to be expressed in these tumor cells." (PMID 39451592, 2024). "The clinical utility of Vimentin relies on its suggested value as a histological biomarker in PDAC due to its surface expression on circulating tumor cells (CTCs)." (PMID 39001424, 2024). "Staining of brain-frozen sections from in situ tumor-bearing mice showed increased E-cadherin expression and decreased vimentin expression in the SECTM1 knockdown group compared with the NC group." (PMID 38164182, 2024). "The biopsy specimens were stained for Ki-67, E-cadherin, vimentin and tumor-infiltrating lymphocytes (TIL, all CD45 positive cells)." (PMID 39707580, 2024). "Glabridin inhibits EMT by upregulating epithelial markers (E-cadherin, occludin) and downregulating mesenchymal markers (vimentin, Zeb1), effectively reducing tumor metastasis." (PMID 39723390, 2024). "Tumor cell uptake of M2 macrophage-derived exosomes leads to downregulation of E-cadherin and upregulation of N-cadherin and vimentin." (PMID 39555068, 2024).
tumor (continued). "Changes in protein levels associated with EMT were observed, including increase of N-cadherin (N-cad) (“cadherin switch”), and decreases of E-cadherin (E-cad), tumor markers vimentin (VM) and fibronectin (FN)." (PMID 39420834, 2024). "Tumor size, as assessed by the total area occupied by cells immunolabelled against human vimentin (hVIM), was significantly reduced in the xenografts derived from the mutant line (18.3%–60.3% vs. 51.8%–71.4%)." (PMID 38848215, 2024). "The current findings underscore the utility of cytokeratin, predominantly expressed in epithelial tumor cells, and vimentin, consistently expressed in spindle tumor cells, as valuable biomarkers in the diagnosis of ECS." (PMID 39234394, 2024). "In terms of immunohistochemical (IHC) staining, most tumor cells have been shown to stain positive for Vimentin, CD10, PAX8, and AMACR." (PMID 39234013, 2024). "Beyond its involvement in tumor cell EMT and metastasis, Vimentin plays a critical role in tumor angiogenesis, immune infiltration, and immune suppression." (PMID 38191501, 2024). "Then, we obtained the subcutaneous tumor tissues for mIHC about the expression of E-cadherin, and Vimentin." (PMID 38980538, 2024). "Immunohistochemical staining of tumors for EpCam (epithelial marker) and vimentin (mesenchymal marker) showed that the fraction of epithelial, EpCam-positive, cells was more than 90% in tumor xenografts and on average 76 ± 10% in patients’ tumors." (PMID 39197048, 2024). "IHC results also showed that Ki67, BCL2, N-cadherin, and vimentin were downregulated, and Caspase3 and E-cadherin were upregulated in p65/S536D-overexpressing tumor tissues." (PMID 39498383, 2024). "Considering that EMT is crucial for initiating the process of tumor metastasis cascade, vimentin and MMP9 have garnered significant attention as essential markers for EMT." (PMID 38388902, 2024). "Immunohistochemically, the tumour cells are positive for evidence of vimentin and neuro-specific enolase." (PMID 39582714, 2024). "Vimentin-positive cells showed intensively at the edges of tumor tissues and rapidly developed tumor growth in zones between adipose and tumor tissues." (PMID 38999849, 2024). "Next, the expression levels of BRCC3, ZEB1, E-cadherin and vimentin in tumor tissues were detected via immunohistochemistry." (PMID 38449391, 2024). "Vimentin plays a crucial role in the acquisition of migratory and invasive capabilities by tumor cells." (PMID 38637902, 2024). "Other studies have reported that the isoflavonoids genistein, biochanin, puerarin, and glabridin regulate the invasive process of tumor cells by increasing the expression of E-cadherin and decreasing the expression of vimentin, Snail, and Twist." (PMID 38737746, 2024). "It was found that both CD44 and E-cadherin decreased with the grade of tumor, while EGFR and vimentin increased with tumor de-differentiation." (PMID 39050298, 2024). "Since the fasting-mimicking condition inhibited expression levels of vimentin protein as an EMT marker in MB-231 cells, we evaluated vimentin-positive cells in tumor tissues." (PMID 38999849, 2024). "A substantial body of research indicates that vimentin is highly expressed in various tumor cells, especially in tumor cells undergoing EMT." (PMID 39927117, 2024). "Increased expression of tumor-promoting genes like VIM (vimentin) and TWIST1 (Twist Family BHLH Transcription Factor 1) vs. baseline was detected with 100 mg/d of aspirin but not with the other two higher doses." (PMID 38495101, 2024). "EMT is a cellular-transformed process marking by changes from E-cadherin–expressing epithelial cells to a mesenchymal phenotype expressing vimentin and N-cadherin, endowing tumor cells to migrate and invade." (PMID 38711855, 2024). "RGS proteins induced the regulation of vimentin and E-cadherin, and involved in the process of tumor metastasis." (PMID 38978046, 2024).
tumor (continued). "When tumor cells show down-regulation of E-cadherin expression, β-conjugated proteins on the cell membrane are transferred to the nucleus, leading to high expression of the mesenchymal cell markers N-cadherin and vimentin, which promotes tumor cell metastasis." (PMID 39450260, 2024). "EMT is a dynamic biological process that is indispensable for tumor cell metastasis and involves the diminution of epithelial proteins (E-cadherin) and the increment of mesenchymal proteins (Twist, Vimentin, and N-Cadherin)." (PMID 38904007, 2024). "Pan-CK was positive in the tumor's epithelial component, while vimentin was positive in high-grade sarcomatous components." (PMID 39588415, 2024). "Immunohistochemistry revealed other Vimentin-positive tumor cells in the lungs, but as the number of cells decreased, the Ki67 positivity rate also decreased, and a single tumor cell was negative for Ki67." (PMID 38978506, 2024). "Immunophenotypic profiling revealed positive expression of vimentin and epithelial membrane antigen in tumor cells, whereas smooth muscle actin and S-100, among others, were negative." (PMID 38961422, 2024). "They found that the tumour emboli entered an intermediary state in which cells gradually lost vimentin expression and shifted towards a phenotype that predominantly expressed E-cadherin." (PMID 38468823, 2024). "Compared to diploid tumor cells, PGCCs and their budding progeny cells exhibit reduced cytokeratin and elevated vimentin levels, indicating an epithelial-mesenchymal transition (EMT) that enhances tumor invasiveness." (PMID 39055650, 2024). "In some cases such as the lymph node metastasis of oral NC, most of the cancer cells within the metastasis tumor expressed not only E-cadherin but also vimentin and ZEB1, showing a mixed epithelial–mesenchymal phenotype." (PMID 38724194, 2024). "Our findings revealed that EMT markers such as E-cadherin and vimentin, as well as the general tumor marker Ki-67, are heterogeneously expressed in BTC cells." (PMID 39668430, 2024). "Compared with the vector group, Ki67, BCL2, N-cadherin, and vimentin were upregulated, and Caspase3 and E-cadherin were downregulated in p65/S536A-overexpressing subcutaneous tumor tissues." (PMID 39498383, 2024). "Biopsies of image guidance were consistent with metastatic adenocarcinoma, which had strong estrogen receptor (ER) positivity and strong vimentin positivity in the cytoplasm of tumor cells." (PMID 39318944, 2024). "DSTN interacts with the cytoskeleton to promote the EMT process in tumor cells, enhancing their migratory capacity, and drives this process by regulating markers such as N-cadherin and Vimentin." (PMID 39896807, 2024). "All samples were positive for the soft‐tissue tumor marker Vimentin, as expected, and the CD34 endothelial cell marker was negative in tumor cells, only marking vessels." (PMID 37798904, 2024). "Immunohistochemical staining of Vimentin in tumor, liver, and lung specimens displayed less metastasis upon ASO therapy and increased metastatic niche in overexpression groups." (PMID 37950038, 2024). "In nude mice xenograft model, PRKCD_pY313 significantly promoted tumor progression, accompanied by increased levels of Ki-67, Bcl-xl and Vimentin, and decreased levels of Bad, cleaved caspase 3 and ZO1, which was opposite to the trend of Y313F group." (PMID 38347536, 2024). "Immunohistochemically, the tumor cells in our three cases exhibited strong positive staining for desmin, vimentin, ER, and PR." (PMID 38590660, 2024). "Detailed immunohistological investigations have allowed for the assessment of specific marker expressions such as Ki-67, CK19, SOX10, and vimentin to validate the tumor microenvironment relevance of the model." (PMID 39329875, 2024). "The addition of cycloheximide (CHX), a widely used translation inhibitor, to the cell culture reversed the upregulation of vimentin expression in the IL-15-overexpressing tumor cells." (PMID 38637902, 2024).
tumor (continued). "CK7 was exclusively expressed in the ductal tumor cells, while VIM was present in most tumor cells lining the ducts and in stromal fibroblasts." (PMID 39682758, 2024). "Vimentin, an intermediate filament protein integral to vimentin adhesion networks, has emerged as a significant EMT marker associated with tumor metastasis." (PMID 38685125, 2024). "Cytoplasmic vimentin positivity suggests that the tumor has acquired some mesenchymal traits, indicative of epithelial-mesenchymal transition (EMT)." (PMID 39677213, 2024). "The IHC markers CK5, vimentin, and p63 are markers of myoepithelial cells (MECs) in both sweat and mammary glands, and they have been used to identify tumor characteristics." (PMID 39765541, 2024). "Vimentin is generally expressed in normal mesenchymal cells and mesenchymal tumor cells, and can weaken epithelial cell adhesion and promote tumor cell invasion and migration." (PMID 38449391, 2024). "Building on the understanding of CSV as a crucial marker and therapeutic target, the role of vimentin, another key player in the tumor microenvironment, becomes particularly significant in the context of metastasis and cancer progression." (PMID 38685125, 2024). "Staining for pan-cytokeratin and vimentin suggested that vimentin+ fibroblasts surrounded cytokeratin+ tumor acini in assembloids as they do in the parent tumor." (PMID 39610249, 2024). "In the same study, the combination was shown to diminish in vivo tumor growth, accompanied by the downregulation of E-cadherin, N-cadherin, and vimentin." (PMID 38254735, 2024). "We then assessed the impact of the combined opposite targeting of p110δ PI3K and RhoA on cancer cells metastasis by determining the tumour cell blood burden and the expression of vimentin in the lungs." (PMID 38182748, 2024). "Immunohistochemical results showed that the tumor cells positively expressed vimentin, SMA, and ALK, which was consistent with the pathological diagnosis of IMT." (PMID 39193013, 2024). "One tumor in our study was only positive for vimentin and NSE, and another one was only positive for vimentin, S100, and SMA." (PMID 38612342, 2024). "The IHC results showed that E-cadherin was upregulated in the combination group, while the expression levels of N-cadherin and vimentin were reduced, indicating that the tumor cells underwent mesenchymal-to-epithelial transition." (PMID 39375945, 2024). "Vimentin expression was present in 46% of the biopsies and was observed in tumor cells surrounding blood vessels." (PMID 38611032, 2024). "Hematoxylin-eosin (HE) staining and IHC results showed that MT1G overexpression correlated with increased expression of Ki67, N-cadherin, and Vimentin, as well as decreased E-cadherin expression in xenograft tumor cells." (PMID 38906969, 2024). "No histologic prognosticator is specific to the insula and most, including vimentin staining and MIB-1/Ki-67 PI, owe their prognostic effect to their association with tumor grade." (PMID 37619597, 2024). "A decreased E-cadherin and increased vimentin expression correlate with high tumour budding and poor prognosis in OSCC." (PMID 39429322, 2024). "Studies have reported that phosphorylation of VIMENTIN at different sites affects the invasion and metastasis ability of tumor cells." (PMID 38459513, 2024). "Vimentin, a mesenchymal cell marker, highlights the mesenchymal properties of tumor cells, which are common in tumors of mesenchymal origin." (PMID 39591300, 2024). "A recent consensus statement written on CAF characterization states that any mesenchymal cell cultured from a tumor that has an elongated morphology and is positive for a mesenchymal marker, such as vimentin, can be considered CAF." (PMID 38883829, 2024).
tumor (continued). "ZEB1, vimentin, and N-cadherin are EMT markers, and their expression is associated with tumor invasive, proliferation, and drug resistance." (PMID 39198318, 2024). "EMT markers, such as E-cadherin, N-cadherin, vimentin, Snail and Slug, play important roles in regulating the invasion and metastasis of tumor cells." (PMID 38886389, 2024). "Immunohistochemistry showed that the sarcomatous tumor cells were specifically positive for vimentin, α-smooth muscle actin, or epithelial membrane antigen." (PMID 38601424, 2024). "Our investigation reveals that a 14-day treatment of tumor cells with BNE-RRC led to a significant decrease in the expression of the mesenchymal marker vimentin." (PMID 39273519, 2024). "First, exposure of normal lung epithelial cell line (NL-20) to REVs and SEVs for 48 hours resulted in increased expression of SLC1A5, EMT marker Vimentin, and other tumor markers." (PMID 39431017, 2024). "Data from the KPV−/− GEMM show that vimentin is required for metastasis and tumor progression, as KPV−/− mice had decreased lung tumor burden, lower-grade tumors, and no metastasis from primary tumors in the flank to the lung." (PMID 37161053, 2023). "In this study, we showed that ROS, phospho-Src, phospho-STAT3, and vimentin were more abundant at the tumor boundary from HNSCC patients." (PMID 36446524, 2023). "HIPK2 can restrain tumor metastasis by downregulating vimentin, a driver for EMT and tumor invasion." (PMID 36831402, 2023). "At the same time, IHC stained tumor sections with E-cadherin and vimentin to quantitatively evaluate EMT related changes." (PMID 38017477, 2023). "Western blot analysis demonstrated that the content of E-cadherin in serum globular tumor tissue decreased, and the expression of N-cadherin and vimentin increased in a murine xenograft model of CRC." (PMID 37639070, 2023). "Histological analysis indicated that the expression of YAP1, TAZ, p62/SQSTM1 and vimentin was also elevated in the tumour tissues of hyperglycemic mice." (PMID 37665055, 2023). "Enhanced vimentin contributes to cytoskeleton organization and focal adhesion stability, thus allowing cancer cells to resist various stresses generated by the tumor microenvironment and promoting the increase of malignancy." (PMID 36672299, 2023). "The signal intensity of phospho-CREB was evaluated in cell masses expressing vimentin as a tumor marker." (PMID 36969081, 2023). "We confirmed the overexpression of vimentin in the tumor vasculature of a panel of dog UC with immunohistochemistry, underscoring the translational relevance of the CVx1 anti-eVim vaccine from mice to dogs." (PMID 37568772, 2023). "Evaluation of the primary ccRCC patient tumours and normal kidney tissues by the CPTAC database showed significantly higher expression of VIM in primary tumours compared to normal kidney tissues." (PMID 37174052, 2023). "Luc-KPV−/− and Luc-KPVY117L cells also developed dense tumors; surprisingly, some cells within the tumor expressed vimentin." (PMID 37161053, 2023). "In mouse tumors, overexpression of FAM171B resulted in increases in the tumor volume and mass, while treatment with Vimentin-IN-1 effectively mitigated this effect." (PMID 37915048, 2023). "TiY treatment induced a significant ablation of the TIC population in the tumor, and further molecular study elucidated that the mechanism of TiY is through vimentin dynamics in TIC." (PMID 36923526, 2023). "qRT-PCR demonstrated that the mRNA expression of PCNA, Vimentin and Twist was downregulated in tumor tissue samples compared with that in the lv-NC group." (PMID 36718644, 2023). "Consistent with our in vitro findings, IHC staining of SPOCK1 and vimentin in tumor tissues from Caki-1-SPOCK1- and Caki-1-shSPOCK1-injected mice showed the upregulation and downregulation of both proteins, respectively, compared to control mice." (PMID 36766694, 2023).